CD4 (CD4 molecule)
Diseases named in the same sentence as CD4 in open-access papers (continued):
Sharing a sentence is not in itself a finding about the gene and the disease.
anemia (continued). "Moreover, to curve the higher burden of undernutrition, emphasis should be given to the prevention and early management of anemia and low CD4 counts by strengthening the usual hemoglobin and CD4 count evaluation." (PMID 27468351, 2016). "Risk factors for anemia in a bivariate model included stunting, CD4 < 25 %, detectable viral load ≥400 copies/ml and absence of ART and vitamin A deficiency." (PMID 26482352, 2015). "We also sought to determine whether time-updated anaemia severity was an independent predictor for incident TB and/or mortality even after adjustment for time-updated CD4 counts." (PMID 25889688, 2015). "While this finding goes hand in hand with the CD4 count disparity between genders, few studies have measured clinical symptoms at presentation, except for one systematic review that included measurements of hemoglobin and assessed patients for anemia." (PMID 26848354, 2015). "In conclusion, this study has shown that HAART initiation, anthelminthic medication, and regular checkup of CD4 count might have benefit in reducing anemia in HIV positive pediatric patients." (PMID 25878898, 2015). "However, the risk for death was higher in patients with bed-ridden functional status, advanced WHO stage, low CD4 count, severe anemia, low BMI, and concomitant TB infection." (PMID 26889319, 2015). "We focused on the association of CD4 counts, WHO stage, anemia, and body weight." (PMID 26295033, 2015). "Out of 191 subjects with anemia in our study, 77% (n = 148) had CD4 count <200." (PMID 25209550, 2014). "However, when adjusted for year of ART initiation, age, baseline CD4 count, baseline anaemia level and NRTI, the difference between sexes was reduced." (PMID 25361827, 2014). "Anaemia in Association with Antiretroviral Use and HIV Disease Stage (CD4 Count <200 cells/mm3)." (PMID 25222119, 2014). "We report the prevalence, type, severity and subsequent incidence of anaemia in a cohort of HIV infected women during pregnancy, within 72 hours post-delivery and 2 weeks post-delivery in association with HIV disease stage (CD4 count) alone or in relation to ARV prophylaxis or treatment." (PMID 25222119, 2014). "We did not observe any association between baseline CD4 count and recovery from anaemia in multivariate analysis." (PMID 25722787, 2014). "Similarly 30.4% (14/46) patients at the age of <25 years old and 35.2% (50/142) of patients with CD4 cell count <200 cells/μl were developed anemia." (PMID 25335859, 2014). "Besides cryptococcal antigenemia, other factors associated with one-year mortality included ART administration, low CD4 cell count, anaemia at baseline, WHO clinical stage 4, BMI<18.5 kg/m2, a high plasma HIV-RNA and oral candidiasis." (PMID 24476751, 2014). "Similarly 12.3% (14/146) patients at the age of 36–45 years old and 18% (18/100) patients with CD4 cell count <200 cells/μl were developed anemia." (PMID 25335859, 2014). "The prevalence of anemia was significantly higher in patients with CD4 cell count <200 cell/μl." (PMID 25335859, 2014). "Mostly, prevalence of anemia is higher among the study participants who have low CD4 count." (PMID 24238076, 2013). "Our findings are further supported by other studies which report that pregnant women are known to exhibit fluctuating CD4 levels in pregnancy, which might expose them to higher helminth infection prevalence leading to maternal anemia." (PMID 23967365, 2013). "Among those with HIV, anemia is a strong risk factor for disease progression and death independent of CD4 count and viral load." (PMID 24069036, 2013). "There were differences in the baseline characteristics of age, residential distance from treatment site, baseline CD4 count, baseline anemia status and anti-retroviral drug regimen between the patients who were lost-to-follow-up and those alive and in the study at 12 months." (PMID 23452915, 2013). "The overall prevalence of anemia increased with decreasing CD4 count (P<0.001)." (PMID 24058490, 2013).
anemia (continued). "Adjusted multivariable analysis, excluding deaths in the first 21 days, showed weight loss >10%, low CD4 count, severe anemia, laboratory-only TB diagnosis, and not initiating ART to be independently associated with increased risk of death." (PMID 23185278, 2012). "Interestingly, we found that this was also true after correction for CD4 cell count, indicating that anemia is an independent factor for HIV disease progression." (PMID 21827653, 2011). "Furthermore, in this population of HIV patients with low CD4+ T Lymphocytes cell count, anemia can be a feature of certain opportunistic diseases, like disseminated mycobacterial infection and parvovirus B19." (PMID 22145054, 2011). "Programmed cell death is considered an important pathway involved in the progressive decline of CD4+ T lymphocytes and in the anemia, granulocytopenia and thrombocytopenia, due to impaired CD34+ hematopoietic progenitor survival, occurring in several patients during HIV-related disease development." (PMID 21612582, 2011). "Independent factors associated with early mortality in 30 (60%) studies included: low baseline CD4 cell count, male sex, advanced World Health Organization clinical stage, low body mass index, anemia, age greater than 40 years, and pre-ART quantitative HIV RNA." (PMID 22220193, 2011). "These include: male sex, low body mass index, anemia, low CD4 count and stage-4 WHO disease." (PMID 22187587, 2011). "The association between anemia and decreased survival has been found to be independent of CD4+ T-lymphocyte count and plasma HIV RNA concentration." (PMID 20727136, 2010). "Thus, the overall severity of anemia was exacerbated by removal of Treg cells from the transferred CD4+ T cell population." (PMID 19006695, 2008). "Importantly, the severity of FV-induced CD4+ T cell-mediated anemia critically depended on the balance between FV-specific pathogenic CD4+ T cells and Treg cells." (PMID 19006695, 2008). "Moreover, the predictors of anemia were sex (female) and Low CD4 (<200count)." (PMID 39480901, 2024). "Therefore, our finding suggests iron deficiency as a possible cause of low CD4 counts (hence low CD4:CD8 ratio) and this seems to occur in a dose-dependent manner since more patients with severe anaemia had low CD4 T-cell counts and CD4:CD8 ratios than those with a mild form." (PMID 35022106, 2022). "The association of anaemia with a low CD4:CD8 ratio, independent of HIV infection, is interesting." (PMID 35022106, 2022). "Bivariate analysis of sociodemographic and clinical variables revealed that low baseline CD4 cell count (crude odds ratio (COR) 1.66, 95% confidence interval (CI) 1.01–2.74) and TDF based ART regimen (COR 1.69, 95% CI 1.12–2.54) were associated with the risk of anemia." (PMID 35333889, 2022). "The increased anemia prevalence in above studies could be due to high proportion of female in Ghana (73%) and Cameroon (73.9%) relative to current study (53.8%) and in study of Cameroon, the patients with CD4 count of ≤200 cells/μl were higher." (PMID 35245289, 2022). "Thus, this study reported that anemia was related to an ethnic minority, age, and CD4 count." (PMID 36474196, 2022). "Besides, anemia has been a strong risk factor for disease progression and subsequent death regardless of a cluster of differentiation (CD4) count and viral load." (PMID 33785009, 2021). "Moreover, the incidence of anemia is strongly associated with poorer prognosis, independent of CD4 count and viral load." (PMID 33177659, 2020). "When used in FeLV or FIV naturally infected cats, rHuIFN-α may improve the clinical status; increase the RBC counts; decrease the anemia; increase the neutrophil and lymphocyte counts, improving the immune response against the virus and secondary infections; and improve the CD4+/CD8+ ratio." (PMID 32825496, 2020). "However, the prevalence of anemia increased as the CD4 T cell count decreased." (PMID 32931523, 2020).
anemia (continued). "Among enrolled participants, change in absolute CD4 count (p-value: Anemia type × Time ≤ 0.0077) and BMI (p-value: Anemia type × Time ≤ 0.0852) over 18 months varied by anemia type whether define at the baseline or current anemia type." (PMID 30935133, 2019). "CD4+ T-Cell status was found not significantly (P > 0.05) associated with anemia in HIV infection." (PMID 31703562, 2019). "Another study demonstrated that low vitD3 status in HIV-infected pregnant women in Tanzania was significantly associated with HIV disease progression, all-cause mortality, and severe anemia, while no change in CD4+ or CD8+ T cell counts was observed at follow-up." (PMID 30634590, 2019). "However, residence, habit of washing before meal, practice of eating uncooked vegetable, taking anti-parasite medication, CD4 category, anemia, anemia status, stool consistency, diarrhea and diarrhea condition showed significant association with prevalence of intestinal parasites." (PMID 31029088, 2019). "Furthermore, HIV patients with anemia are at a greater risk of mortality compared to their non-anemic counterparts, even after controlling for CD4+ cell count and viral load." (PMID 25551656, 2014). "In univariable analysis, several risk factors met the pre-defined criteria for inclusion in the multivariable model, but notably TB in the first year of ART and CD4 cell count (baseline or time-updated) did not demonstrate associations with anaemia after 12 months of ART." (PMID 25528467, 2014). "Thus, LAM ODs correlated with more severe anaemia, CD4 lymphocytopenia and neutrophilia." (PMID 25075867, 2014). "Thus, the assay might best be used to screen in a targeted fashion HIV-infected patients with low CD4 counts and those with other poor prognostic characteristics such as moderate or severe anemia." (PMID 24168211, 2013). "Lack of FV specificity in Treg cells suppressing anemia induction by pathogenic FV-specific CD4+ T cells also raised the important question of whether or how Treg cells were being activated to mediate this suppression." (PMID 19006695, 2008). "If so, then CD4+ T cells from nontransgenic wild-type donors, in which the frequency of FV-specific pathogenic clones would be physiologically very low (<10−5) but the frequency of Treg cells is normal (10−1), should not induce anemia." (PMID 19006695, 2008). "CD23-Rock1 mice furthermore developed more severe disease as indicated by persistent anemia, thrombocytopenia, increases in IFN-γ–producing CD4+ T cells, and increased spleen weight at day 21 pi and required early euthanasia." (PMID 39903532, 2025). "Laboratory investigations revealed anemia, elevated CRP, and ESR, with a CD4 count of 441 cells/mcL." (PMID 40024178, 2025). "Additionally, the absence of anaemia was significantly associated with normal CD4 levels." (PMID 40684209, 2025). "Anemia, WHO clinical stage, CD4 cell count, and delayed developmental milestones were independent predictors of mortality." (PMID 39854472, 2025). "Sb showed superiority in reducing anemia and TNF-α and elevating CD4 and DRD1 gene expression and improving brain histopathological alteration compared to dark chocolate." (PMID 40615531, 2025). "Among these; low CD4 count, advanced WHO stages, Anemia, undernutrition, missing of cotrimoxazole and isoniazid preventive therapy, immunosuppression." (PMID 38968268, 2024). "This variability arose from differences in definitions and measures of anemia and HIV disease severity, such as CD4 count cut-points, viral load, and clinical staging." (PMID 40084227, 2024). "In the bi-variable Cox regression analysis, age, status of parents, educational status, initiation of ART within seven days, CD4, WHO staging, anemia, weight for height Z score, ART adherence, and CPT were candidates for multivariable analysis." (PMID 39232814, 2024). "In this study, predictors for anemia among patients with Dolutergravir based treatment were sex, WHO clinical stage, and CD4 count." (PMID 39480901, 2024).
anemia (continued). "The present study found that CD4 count, WHO clinical staging, cotrimoxazole prophylaxis and MUAC were significant predictors of anaemia among seropositive children after starting HAART." (PMID 37706072, 2023). "Higher BMI was associated with lower Hb, HCT, albumin, and WBCs, whereas the decreased levels of hemoglobin and HCT point to anemia, known to be prevalent in HIV patients, and the reduction in CD4+ T cell count indicates immunosuppression in the patients." (PMID 37736888, 2023). "Lower CD4 counts, being female, and being co-infected with PM, HCV, or TB were independent correlates of anemia in hospitalized people living with HIV." (PMID 36474196, 2022). "Anemia prevalence in patients with CD4 count of 200–499 cells/μl was 45.1% (32.2% in MHC and 12.9% in OH) and it varies significantly in CD4 count between 200–499 in MHC and OH (P≤0.01, 99% CI)." (PMID 35245289, 2022). "In total study participants, significant positive correlation was observed between CD4 count with MCV, CD4 count with MCH and CD4 count with anemia." (PMID 35245289, 2022). "Anemia prevalence was undeniably higher and disproportionately higher in MHC, in female sex, in patients with CD4 count of ≤500 cells/μl." (PMID 35245289, 2022). "The positive control suffered from microcytic hypochromic anemia, thrombocytopenia, leukocytosis, a decrease in L/N ratio, increased CRP level, severe histopathological changes, and decreased CD4+ expression, and an increase in CD8+ and COX-2 expression." (PMID 35698524, 2022). "There were significant difference in anemia in MHC and OH infected with different CD4 group (P≤0.01, 99% CI)." (PMID 35245289, 2022). "Low baseline CD4 cell count and TDF based ART regimen were found to be independent predictors of anemia; while being educated was protective." (PMID 35333889, 2022). "Male sex was the only independent predictor of attrition identified (adjusted Hazard Ratio, aHR 2.18, 95% CI 1.10 to 4.34) adjusted by age, severe anaemia, CrAg positivity, TB‐LAM positivity and CD4 count." (PMID 34347366, 2021). "Poor trials were found for ORR, DCR, QOL, myelosuppression, neutropenia, thrombocytopenia, anemia, gastrointestinal toxicity, liver toxicity, renal toxicity, neurotoxicity, CD3+ T cells, CD3+ CD4+ T cells, CD4+/CD8+ T cell ratios, and natural killer cells." (PMID 34122057, 2021). "Anaemia and neutropaenia are the major types of toxicity of AZT use particularly in those patients with baseline anaemia or neutropaenia, CD4 count ≤ 200 cells/mm3." (PMID 34583644, 2021). "This meta-analysis indicated that anemia, WHO clinical staging of three and four, and low CD4 cell counts were of significant effects for the high incidence of TB among HIV-positive patients receiving ART." (PMID 33632342, 2021). "Factors increasing the risk of the composite unfavourable outcome under both interventions were aged 16 to 24 years, being unmarried, anaemia, ART initiation on the same day as HIV care enrolment and CD4 ≤ 100 cells/mm3." (PMID 32128964, 2020). "After adjustment for confounding variables using multivariate logistic regression modeling, anemia was independently predicted by age ≥50 years, WHO clinical stage IV HIV disease and CD4 count < 200 cells/mm3." (PMID 30759131, 2019). "Lower CD4+ T-cell count and WHO clinical stage IV HIV disease were identified as independent predictors for presence of anemia, leucopenia and thrombocytopenia." (PMID 30759131, 2019). "Pre-ART survival was poorer for patients who were older, had lower CD4, and had anemia; on-ART survival was poorer for patients living outside the city and who had anemia." (PMID 31237899, 2019). "It is associated with a rapid decline (of ≥2 logs) in HIV viral load, a low nadir and then rising CD4+ count following ART introduction, and anemia." (PMID 28931222, 2017). "In this study the moderate to severe anemia was strongly predicted by AZT based regimen, advanced clinical stage, low baseline CD4 and macrocytosis." (PMID 27200131, 2016).
anemia (continued). "Additional predictors of early drug substitutions were CD4 at switch to second-line ART, anaemia, reporting a possible ADR and being late for a scheduled visit during follow-up period." (PMID 28364563, 2016). "Having intestinal parasitic infections (AOR = 2.7, 95% CI, 1.1–7.2), having lower CD4+ T cell count (AOR = 3.8, 95% CI, 1.6–9.4), and being HAART naïve (AOR = 2.3, 95% CI, 1.6–9.4) were identified as significant predictors of anemia." (PMID 25878898, 2015). "We found that time-updated moderate or severe anaemia during ART were the strongest independent predictors for both incident TB and death during ART and, notably, were of greater predictive value than CD4 cell counts." (PMID 25889688, 2015). "In contrast to CD4 T cell depletion, depletion of both NK and NKT cells or CD8 T cells conferred protection against anemia." (PMID 26070118, 2015). "Intestinal parasitic infections, lower CD4+ T cell count, and being HAART naïve were identified as significant predictors of anemia." (PMID 25878898, 2015). "For example, a woman with anemia created a table to track her blood test results over time, 2 patients with HIV kept records of their CD4 count values over time, and many patients checked on their cholesterol regularly." (PMID 26290186, 2015). "Anemia and syphilis screening was studied in 1673 eligible records of HIV-positive and HIV-negative women, while CD4 cell counting was investigated in files of 759 eligible HIV-positive women." (PMID 26308345, 2015). "This study, therefore, aims to evaluate the magnitude of anemia among pediatric HIV positive patients based on age, gender, HAART status, intestinal parasitic infection, and CD4+ T cell levels." (PMID 25878898, 2015). "Based on the present finding, HIV patients are recommended to check up their CD4 cell counts regularly and start HAART when it is appropriate in order to decrease the prevalence of anemia." (PMID 25335859, 2014). "Although we performed a control for other predictors of mortality, such as anemia, weight loss, and a low CD4 count, the occurrence of residual confounding is very likely as the measurements were not conducted very frequently: for example, on average, a CD4 count was measured every 6 months." (PMID 24679187, 2014). "Prevalence of anemia was high in HAART naïve patients while leucopenia and neutropenia prevalence was higher in patients on HAART and their prevalence increased as the CD4 count decreased." (PMID 24666771, 2014). "A higher count of CD3+, CD4+, and CD19+ cells coexpressing TLR7 was found in patients with anemia compared to subjects with hemoglobin above 12 g/dL." (PMID 24692849, 2014). "Several studies from Africa and Ethiopia have shown that anemia is an independent predictor of mortality in patients on ART, even after controlling for CD4 cell count." (PMID 27351014, 2014). "Based on the present finding, HIV patients are recommended to check up their CD4 counts regularly and to start HAART when it is appropriate in order to decrease the prevalence of anemia." (PMID 24666771, 2014). "This study therefore seeks to evaluate the prevalence of anaemia and the related factors among HAART-naïve HIV positive patients at different age groups, gender and CD4 levels." (PMID 24238076, 2013). "The baseline median CD4 cell count was 142 cells/mm3 (IQR: 85–223), baseline median hemoglobin level was 10.9 g/dl (IQR: 9.3-12.4) and anemia based on hemoglobin less than 10 g/dl was common (n=192; 35.2%)." (PMID 23452915, 2013). "Vitamin D deficiency was more prevalent in patients with hypoalbuminemia (97.4%), anemia (86.1%), HIV co-infected patients with CD4 count <200cells/mm3 (83.2%) and hypocalcemia corrected for serum albumin levels (67%)." (PMID 23886009, 2013). "In the sickest patients with the lowest CD4 cell counts, highest CRP concentrations or severe anemia, the sensitivity of a single Xpert MTB/RIF test was more than twice that of smear microscopy." (PMID 24168211, 2013).